CMTM6 (CKLF like MARVEL transmembrane domain containing 6)
Diseases named in the same sentence as CMTM6 in open-access papers (continued):
Sharing a sentence is not in itself a finding about the gene and the disease.
tumor (continued). "CMTM6 is involved in multiple tumor-related signaling pathways and is closely related to various tumor-infiltrating cells." (PMID 36643629, 2023). "Western blotting and qRT-PCR analyses revealed that the relative levels of CMTM6 expression in fresh BC tissues were significantly higher than that in the matched adjacent non-tumor tissues (P < 0.001)." (PMID 36627608, 2023). "Previous studies have shown that HuR regulates the stability of CMTM6, which can promote tumor metastasis through various mechanisms such as affecting epithelial–mesenchymal transition (EMT), activating immune cells, and regulating signaling pathways." (PMID 37592296, 2023). "These in vivo findings align with the in vitro data and suggest that the expression of CMTM6 in tumor cells contributes to the response to T cell-based immunotherapy by modulating CD58 expression levels." (PMID 37683639, 2023). "In tumor-induced immunosuppression, CMTM6 has become an importantly potential immune checkpoint, indicating its new possibilities for overcoming tumor immune resistance." (PMID 37726578, 2023). "GO assessment indicated that expression of CMTM6 was enriched in the immune response to tumor cells, interleukin-1-mediated signaling pathway, inflammatory cell apoptotic process, and T-cell chemotaxis." (PMID 37726578, 2023). "CMTM6 is a critical regulator of PD-L1 stability in a broad range of cancer cells, and CMTM6 stabilizes PD-L1 protein to promote tumor immune escape." (PMID 36627608, 2023). "They highlight the critical roles of tumor-intrinsic CMTM6 and CD58 expression in modulating T cell-tumor cell interactions and their potential impact on T cell-based immunotherapy." (PMID 37683639, 2023). "CKLF-like MARVEL transmembrane domain-containing 6 (CMTM6) has been considered as a new immune checkpoint for tumor-induced immunosuppression." (PMID 36627608, 2023). "Recently, more and more studies have been reported the detailed mechanism of CMTM6 participating in regulating tumor immunity." (PMID 37726578, 2023). "Patients with high CMTM6 expression on tumor cells and/or in the TME showed a survival benefit compared to their CMTM6-low counterparts." (PMID 38067301, 2023). "Previous researches have reported that CMTM6 promotes tumor progression via modulation of immunity of T cells in a variety of tumors." (PMID 37726578, 2023). "CMTM6 mRNA transcripts in BC tissues were significantly higher than that in the corresponding non-tumor tissues (P < 0.001)." (PMID 36627608, 2023). "CMTM6 knockdown (resulting from PD-L1 downregulation) significantly promotes tumor-specific T cell activity both in vivo and in vitro." (PMID 36627608, 2023). "CMTM6 has been revealed to be an important regulator of PD-L1 that is involved in immune surveillance in tumor immunity escape in current research." (PMID 37726578, 2023). "Chemokine-like factor-like MARVEL transmembrane domain containing 6 acts as a stabilizer of PD-L1, and the expression of CMTM6 is closely related to the tumor microenvironment." (PMID 36698778, 2022). "Inhibiting CMTM6 expression can diminish PD-L1 expression and greatly limit the tumor cell’s ability to block T cell activity, but it has little effect on the MHC class I molecules." (PMID 35907881, 2022). "Recently, CMTM4 and CMTM6 are identified as PD-L1 regulators to regulate PD-L1 stability during the immune process in many tumor cells, and thus expected to be a new target for tumor immunotherapy." (PMID 35986302, 2022). "In tumor cells, CMTM6 is involved in BCLAF1-dependent PD-L1 upregulation through inhibition of ionizing radiation-induced PD-L1 ubiquitination." (PMID 35907881, 2022). "CMTM6 can shuttle to macrophages through tumor cell-derived exosomes, which induces M2-like macrophage polarization." (PMID 35958549, 2022).
tumor (continued). "For example, it has been proven that CMTM3, CMTM4, CMTM5 and CMTM7 are new potential tumor suppressors, and interestingly, patients with high CMTM6 expression have a worse survival prognosis than those with low CMTM6 expression according to this study." (PMID 35983975, 2022). "The stability regulation of CMTM6/PD-L1 on gene group RNA indirectly proves that CMTM6/PD-L1 plays a more important role in tumor development and the survival status of tumor cells themselves." (PMID 35845949, 2022). "Most previous studies have shown the tumorigenicity of CMTM6 in the development and progression of cancer; there are few studies that discussed the tumor-suppressive effect of CMTM6." (PMID 35174213, 2022). "Our study presents a novel mechanism that stabilizes p21 protein and reveals CMTM6 as a pivotal suppressor in HCC tumor progression and TACE-resistance." (PMID 35304440, 2022). "In this study, we identified CMTM6 as a tumor suppressor in HCC that can inhibit the HCC cell proliferation by blocking G1/S transition." (PMID 35304440, 2022). "The expression of CMTM6 plays an important role in tumor progression, but its role in GMB is unclear." (PMID 36698778, 2022). "In TNBC, CMTM6 expression is positively correlated with tumor size, lymph node metastasis, Ki67 proliferation index, and TNM stage (p < 0.05)." (PMID 35845949, 2022). "Regarding different tumor stages, higher expression of CMTM6 only appeared beneficial to OS and PFS in the first stage of OV patients." (PMID 35174213, 2022). "Recently, CMTM6 has been found to play multiple roles in tumor progression but different studies have reached completely opposite conclusions." (PMID 35304440, 2022). "Due to high expression of PD-1/PD-L1 in tumor-infiltrating T cells, CMTM4 and CMTM6 are thought to be important players in the tumor microenvironment and anti-tumor immunity." (PMID 35986302, 2022). "CMTM6 protects PD-L1 from lysosomal-mediated degradation, increases its stability, and enhances the ability of tumor cells to suppress immune responses." (PMID 35907881, 2022). "CMTM6 expression is positively correlated with tumor size, lymph node metastasis, Ki67 proliferation index, and TNM staging (p < 0.05)." (PMID 35845949, 2022). "In conclusion, it was earlier established that CMTM6 is a novel protein, which stabilizes PD-L1 and potentiates the immune evasion by tumor cells." (PMID 33434185, 2021). "CMTM6 can also activate and chemotax a large number of immune cells and affects the proliferation and invasion of tumor cells." (PMID 33509216, 2021). "Overall, these studies suggest that CMTM6 is an important factor for immune invasion by tumor cells." (PMID 33434185, 2021). "For example, POLE/POLD1 gene mutations are associated with microsatellite instability (MSI), mismatch repair (MMR), and TMB, and CMTM6 is related to PD-L1 expression and regulation of anti-tumor immunity." (PMID 34790698, 2021). "This indicates that the regulation of CMTM6 and PD-L1 signaling pathway in the tumor microenvironment has a synergistic effect." (PMID 33509216, 2021). "Many studies have explored the relationship between CMTM6 and tumour immunity, indicating that CMTM6 as a promising target for cancer immunotherapy." (PMID 33757532, 2021). "Summarily, our study unraveled the importance of HuR in tumor immune evasion via regulating CMTM6-PD-L1 axis." (PMID 33649535, 2021). "We observed that in the CMTM6 knockdown group, the tumour cells were arranged more loosely (as shown by H&E staining), and the expression of Ki-67 had decreased significantly." (PMID 33757532, 2021). "CMTM6 is a critical regulator of cell surface expression of PD-L1 in tumor cells, but little is known about the transcriptional regulation of CMTM6." (PMID 33803139, 2021). "The results of the present study implicated CMTM6 in the migration and invasion of HCC cells, thus improving our understanding of CMTM6’s function in tumours and suggesting that CMTM6 is a therapeutic target to treat HCC." (PMID 33757532, 2021).
tumor (continued). "Our data uncovered the inhibitory effect of HuR on immune activation and highlighted the critical contributions of HuR to tumor progression in vivo via up-regulation of CMTM6-PD-L1 axis." (PMID 33649535, 2021). "Inhibition of CMTM6 led to decreased PD-L1 protein levels and enhanced tumour-specific T-cell activity." (PMID 33757532, 2021). "CMTM6 is a PD-L1 protein regulator that helps maintain the expression of PD-L1 while regulating tumor immunity." (PMID 34930244, 2021). "The levels of CMTM6 mRNA and protein were both applied for the prognosis analysis of different types of tumor and contradictory conclusions were obtained." (PMID 34680324, 2021). "CMTM6 has been established as another important immune checkpoint and regulates the anti-tumor immune effect mediated by T lymphocytes." (PMID 33509216, 2021). "In conclusion, we herein report that CMTM6 is heterogeneously expressed in diverse cancers and its expression is correlated with the tumor immune microenvironment and pan-cancer prognosis." (PMID 33552963, 2020). "We investigated the relationship between CMTM6 expression and immune cell infiltrates in the tumor microenvironment using CIBERSORT." (PMID 33552963, 2020). "Pan-cancer analysis of CMTM6 protein expression in 20 tumor types was performed using a cohort from the Human Protein Atlas (HPA)." (PMID 33552963, 2020). "The role of CMTM6 in anti-tumor immunity and stabilization of the expression of PD-L1 has prompted us to explore its role in GC." (PMID 32874775, 2020). "Because the depletion of CMTM6 enhanced tumor-specific T cell responses by reducing PD-L1 expression, CMTM6 has gained attention not only as a key molecule involved in the PD-1/PD-L1 axis but also as a potential therapeutic target against cancers." (PMID 32596272, 2020). "Two recent articles have identified CMTM6, which is a PD-L1 regulatory factor that plays an important role in inhibiting T-cell activation and anti-tumor responses." (PMID 32874775, 2020). "Additional studies including a large number of samples, in addition to other cancer types, are necessary to clarify the importance of CMTM6 in the tumor microenvironment of canine cancers." (PMID 32596272, 2020). "Taken together, these findings highlight that CMTM6 plays an important role in the tumor immune microenvironment, and CMTM6 has been identified to have prognostic value in some types of cancers." (PMID 33552963, 2020). "CMTM6 was identified as a major regulator of PD-L1, a key immunological checkpoint, and a potential therapeutic target for tumor cell immune evasion." (PMID 32874775, 2020). "The correlation between CMTM6 expression and tumor-infiltrating immune cells differed for different cancers." (PMID 33552963, 2020). "Expression of CMTM6 was reported to limit anti-tumor immunity via regulating abundance and localization of programmed death ligand-1 (PDL1/CD274) at the surface of cancer cells, at least in vitro." (PMID 32908139, 2020). "CMTM6 depletion, via the reduction of PD-L1, significantly alleviates the suppression of tumor-specific T cell activity in vitro and in vivo." (PMID 31646201, 2019). "Decrease of CMTM6 expression downregulated PD-L1 protein level in a wide range of human tumor cells and in primary human dendritic cells." (PMID 29910728, 2018). "Hence, we first analyzed the relationship between CMTM6 expression and tumor-infiltrating immune cells using the GEO dataset GSE63514 (n = 104)." (PMID 40761779, 2025). "Building on these results, we speculated that CMTM6 might play a role in shaping the tumor immune microenvironment in CC." (PMID 40761779, 2025). "CMTM6 has been identified as a key regulator of immune evasion in tumor cells." (PMID 40191195, 2025). "To assess whether the suppression of tumor growth following CMTM6 knockdown is attributable to a reduction in macrophage-mediated effects, we employed anti-F4/80 (α-F4/80) antibody to deplete macrophages in the TC-1 tumor model." (PMID 40761779, 2025).
tumor (continued). "However, this duality becomes apparent in immunotherapy-resistant tumors, where heightened expression of CMTM6 is a telltale sign of tumor resistance and unfavorable prognosis." (PMID 40761779, 2025). "Indeed, it has been shown that knockdown of CMTM6 in tumor models led to a significant reduction in PD-L1 levels, thereby enhancing T-cell-mediated anti-tumor responses." (PMID 41425548, 2025). "Additionally, researchers have discovered that CKLF-like MARVEL transmembrane domain-containing 6 (CMTM6) stimulates the production of Programmed Death-1 (PD-L1) in tumor cells as a defensive mechanism against T lymphocytes." (PMID 40875079, 2025). "Targeting CMTM6 could reduce PD-L1 abundance in tumor cells, diminishing their capacity for immune evasion." (PMID 40507229, 2025). "Notably, the most pronounced attenuation of tumor progression occurred when CMTM6 knockdown was combined with macrophage depletion." (PMID 40761779, 2025). "Disrupting CMTM6 function, for example, could destabilize PD-L1, weakening tumor immune evasion and enhancing the T-cell-mediated destruction of cancer cells." (PMID 40507229, 2025). "Notably, CMTM6 deletion significantly decreases the inhibition of tumor-specific T cell activity by reducing PD-L1 expression." (PMID 40179060, 2025). "Moreover, CMTM6 also regulates PD-L1 in tumor-infiltrating immune cells, such as macrophages and dendritic cells, further amplifying its role in creating an immunosuppressive tumor microenvironment." (PMID 40507229, 2025). "In addition to its macrophage-dependent effects, our data also suggest that CMTM6 exerts tumor-intrinsic functions." (PMID 40761779, 2025). "Notably, the combination of sh-CMTM6-Exos and RS504383 resulted in the most significant tumor suppression, suggesting a potential additive or synergistic interaction between exosomal CMTM6 and CCL2 signaling in promoting CC progression." (PMID 40761779, 2025). "Similarly, tumor growth curves demonstrated that WWP2 knockdown markedly suppressed tumor growth, which was also rescued by CMTM6 knockdown." (PMID 41387673, 2025). "The findings of this study reveal a critical role of CMTM6 in the tumor microenvironment." (PMID 40761779, 2025). "However, it is uncertain if HSC70 and CMTM6 impact macrophage tumor immunity through lysosomal degradation regulation." (PMID 41361104, 2025). "The relationship between CMTM6 expression and a range of clinicopathological parameters was systematically evaluated and found that CMTM6 expression exhibited a significant positive correlation with both tumor size and stromal invasion." (PMID 40761779, 2025). "It has been reported that high expression of CMTM6 is more common in tumor biopsy tissues from CC patients compared with adjacent normal tissues, and CMTM6 high vs. CMTM6 low tumor status was correlated with decreased patient overall survival time after surgery." (PMID 39335098, 2024). "Additionally, heightened CMTM6 expression corresponded to larger tumor sizes, especially in tumors exceeding 5 cm, suggesting its role in promoting tumor progression." (PMID 38495487, 2024). "Since liver metastasis significantly contributes to the death of CRC patients, we next investigated whether CMTM6 promoted CRC liver metastasis in a portal vein tumor injection mouse model." (PMID 39218981, 2024). "Combined with our prediction results, we speculated that CMTM6 may participate in a variety of tumor signal-related pathways by affecting the activity of tumor-infiltrating cells." (PMID 36643629, 2023). "Furthermore, tumor-secreted exosomal CMTM6 was reported to induce M2-like macrophage polarization, indicating an active crosstalk between tumor and immune cells." (PMID 38067301, 2023). "CMTM6 is an important immune-related gene, and we speculate that it may have a regulatory effect on the tumor microenvironment." (PMID 36643629, 2023).
tumor (continued). "By comparing the functional outcome of individual or dual suppression of PD-L1 and CD58 in CMTM6-proficient and -deficient tumor cells in the T cell-tumor coculture, we revealed that CD58 expression is crucial for effective T cell-tumor cell interactions and response to PD-L1 inhibition." (PMID 37683639, 2023). "In contrast, PD-L1 loss in tumor cells did not result in an obvious increase in the levels of CD58 or CMTM6/CD58 interactions." (PMID 37683639, 2023). "Recent reports have identified CMTM6 as a new immune checkpoint in tumor-induced immunosuppression, suggesting that targeting CMTM6 may be a novel approach to overcome tumor immune escape." (PMID 36627608, 2023). "CMTM6 is also involved in immune cell activation and tumor immune responses." (PMID 37726578, 2023). "In addition, the high expression of CMTM6 is closely related to the tumor microenvironment and immunotherapy, providing new ideas for the treatment of posterior LUAD." (PMID 36643629, 2023). "However, the role of CMTM6 expression in the GBM tumor microenvironment is unclear, so we analyzed the relationship between CMTM6 and GBM immune cells." (PMID 36698778, 2022). "Besides, further exploration was carried out to estimate the status of CMTM6 in the tumor microenvironment using TIMER 2.0, TISIDB, and GEPIA2 databases." (PMID 35174213, 2022). "Even if the recurrent tumor specimens are unavailable, the expression level of CMTM6 in the initial tumors can be used to preliminary determine whether a patient is suitable for TACE treatment." (PMID 35304440, 2022). "High levels of CMTM6 may inhibit the anti-tumor immune response of T cells in GBM, so the overexpression of CMTM6 is associated with poor prognosis and short overall survival of GBM patients." (PMID 35370869, 2022). "CMTM6 may be a potential target for immune sensitization therapy due to its capacity to simultaneously regulate tumor cell dryness, EMT, and immune response." (PMID 35897925, 2022). "Taken together, these results indicated that CMTM6 might act as a tumor suppressor and be a useful prognostic biomarker in HCC." (PMID 35304440, 2022). "Importantly, we analyzed the expression of CMTM6 in GBM in relation to tumor-infiltrating lymphocytes (TILs), immunoinhibitors, immunostimulators, chemokines and chemokine receptors." (PMID 36698778, 2022). "The results suggested associations between tumor purity (r = 0.164, p = 9.38e-03), CD4+ T cell (r = 0.263, p = 2.64e-05), neutrophils (r = 0.199, p = 1.60e-03), and myeloid dendritic cells (r = 0.162, p = 1.05e-02) by CMTM6 expression." (PMID 35174213, 2022). "Notably, increasing evidence proves that CMTM6, a regulator of PD-L1, can maintain the expression of PD-L1 and enhance the ability of PD-L1 expression in tumor cells to inhibit T cells." (PMID 36568362, 2022). "Th1, Tfh, Th17, and M1 in OV also forecasted favorable prognosis, and the study suggested that CMTM6 might recruit and regulate T cell and macrophage function to affect tumor regression in OV." (PMID 35174213, 2022). "Their results indicated that CMTM6 protein may promote tumor immune escape in HNSCC by inhibiting the function of effector T cells." (PMID 35958549, 2022). "Recent evidence indicated that tumor-derived EVs can be a potential cancer immunotherapy biomarker which speculating that exosomal CMTM6 is a potential safety biomarker." (PMID 35958549, 2022). "The CMTM6 depletion significantly decreases tumor-specific T cell activity." (PMID 36046788, 2022). "Meanwhile, via the Wnt/β-catenin signaling pathway, CMTM6 may increase tumor cell dehydration and EMT." (PMID 35897925, 2022). "CMTM6 is a membrane protein that co-localizes with the immune checkpoint molecule PD-L1 on the cell membrane to protect PD-L1 from degradation, thereby promoting tumor immune escape." (PMID 35646697, 2022).